ARHGAP18 (Rho GTPase activating protein 18)
Description:
Rho GTPase activating protein that suppresses F-actin polymerization by inhibiting Rho. Rho GTPase activating proteins act by converting Rho-type GTPases to an inactive GDP-bound state. Plays a key role in tissue tension and 3D tissue shape by regulating cortical actomyosin network formation. Acts downstream of YAP1 and inhibits actin polymerization, which in turn reduces nuclear localization of YAP1. Regulates cell shape, spreading, and migration.
Synonyms: MacGAP; bA307O14.2; SENEX
Tractability: Antibody: its Gene Ontology location is reachable by antibodies, with high confidence. PROTAC: ubiquitination databases record sites on it; its protein half-life has been measured.
Gene: Protein-coding gene on chromosome 6 (129,576,132 to 129,710,247, reverse strand). Ensembl gene ENSG00000146376.
Subcellular location: Cytoplasm
Subcellular location (Human Protein Atlas): Cytosol; Nuclear speckles; Plasma membrane
Pathways (Reactome):
Signal Transduction: RHOA GTPase cycle; RHOC GTPase cycle
Gene Ontology:
Molecular function: cadherin binding; GTPase activator activity
Biological process: regulation of actin cytoskeleton organization; regulation of actin filament polymerization; regulation of cell motility; regulation of cell shape; regulation of small GTPase mediated signal transduction; small GTPase-mediated signal transduction; signal transduction
Cellular component: cytoplasm; cytoplasmic microtubule; cytosol; ruffle
Genetic constraint (gnomAD): Loss-of-function variants: 61 observed, 81.09 expected, observed/expected ratio (o/e) 0.75, 90% interval 0.61 to 0.93. The upper end of that interval is the gene's LOEUF score, 0.93, which puts it in group 3 of 6, group 1 being the genes least tolerant of losing a copy. Missense variants: 656 observed, 764.44 expected, observed/expected ratio (o/e) 0.86, 90% interval 0.8 to 0.92. Synonymous variants: 271 observed, 275.12 expected, observed/expected ratio (o/e) 0.99, 90% interval 0.89 to 1.09.
Homologues: Orthologues: chimpanzee ARHGAP18 (99% identical), macaque ARHGAP18 (97% identical), pig ARHGAP18 (91% identical), rabbit ARHGAP18 (90% identical), dog ARHGAP18 (90% identical), guinea pig ARHGAP18 (88% identical), rat Arhgap18 (86% identical), mouse Arhgap18 (85% identical), tropical clawed frog arhgap18 (65% identical), zebrafish arhgap18 (44% identical), Drosophila melanogaster conu (23% identical). Paralogues in human: ARHGAP28 (44% identical), ARHGAP40 (36% identical), ARHGAP19 (16% identical).
Diseases named in the same sentence as ARHGAP18 in open-access papers:
ARHGAP18 is named in the same sentence as 23 diseases in open-access papers, as found by Europe PMC text mining. Sharing a sentence is not in itself a finding about the gene and the disease. The quoted sentences say what the papers report.
schizophrenia (9 papers, 2012 to 2023). A major psychotic disorder characterized by abnormalities in the perception or expression of reality. "Another group reported an association between SNPs in ARHGAP18 and schizophrenia in Caucasian people." (PMID 37958606, 2023). "In stage one, we screened SNPs in ARHGAP18 from GWAS data, and discovered four SNPs, rs7758025, rs9483050, rs9492347 and rs12197901, associated with schizophrenia." (PMID 28384650, 2017). "Genotype and allele frequencies of thirty-two SNPs in the ARHGAP18 gene of schizophrenia patients and controls." (PMID 28384650, 2017). "We then re-tested the four ARHGAP18 SNPs associated with schizophrenia in an independent validation cohort of 860 patients and 860 controls." (PMID 28384650, 2017). "Herein, we describe associations between ARHGAP18 polymorphisms and schizophrenia in a Chinese Han population." (PMID 28384650, 2017). "Through the combinatorial use of a genome-wide screening and neuroimaging, single nucleotide polymorphisms (SNPs) within ARHGAP18 were associated with schizophrenia." (PMID 28384650, 2017). "Herein, we evaluated the association of ARHGAP18 polymorphisms and schizophrenia in a large Chinese Han population of SZ patients and matched controls." (PMID 28384650, 2017). "Single-nucleotide polymorphisms (SNPs) in ARHGAP18 are associated with schizophrenia." (PMID 37958606, 2023). "As a result, they have identified ARHGAP18 as a schizophrenia associated gene." (PMID 30934641, 2019). "Although the functions of ARHGAP18 in the central nervous system are presently unknown, recent studies have shown a potential correlation between genetic polymorphisms of ARHGAP18 and the occurrence of schizophrenia." (PMID 28384650, 2017). "Others participate in neurodegenerative conditions; PD, schizophrenia, and intellectual disability (Tenm4, Pde4dip, Grid2, Arhgap18)." (PMID 36902345, 2023). "We selected a total of thirty-five SNPs in ARHGAP18 for genotypic distribution analysis in 528 patients with schizophrenia and 528 healthy controls." (PMID 28384650, 2017). "Recently, several variants of RhoA-associated GAPs, including ARHGAP10, ARHGAP18, and p250GAP, and GEFs such as KALRN and ARHGEF11, were reported to be significantly associated with the development of schizophrenia." (PMID 37958606, 2023). "Notwithstanding the identification of ARHGAP18 in a genome-wide association study for schizophrenia, it had not been previously connected to cognitive abilities until the present study." (PMID 23082141, 2012). "Collectively, our data suggest the ARHGAP18 may confer vulnerability to SZ in the Chinese Han population, providing additional evidence for the involvement of neurodevelopmental dysfunction in the pathogenesis of schizophrenia." (PMID 28384650, 2017). "These are associated with a variety of neurological diseases, such as cognitive defects (ARHGAP15), migraine without aura (ARHGAP28), AD (ARHGAP2), schizophrenia (ARHGAP18), and bipolar disorder (BD; ARHGAP29; Niftullayev and Lamarche-Vane, 2019)." (PMID 35783123, 2022).
breast cancer (7 papers, 2011 to 2024). A primary or metastatic malignant neoplasm involving the breast. "We demonstrated that increased RhoA activation through decreased ARHGAP18 expression caused a decrease in cell proliferation compared with control cells that have decreased RhoA activity in breast cancer." (PMID 32992837, 2020). "In terms of Rho GTPase regulators, Aleskandarany and colleagues found that the expression of ARHGAP18, a RhoA-specific GAP, is associated with improved prognosis for patients with breast cancer." (PMID 32992837, 2020). "In breast cancer research, the interaction between ARHGAP18 and miR‐200b is particularly notable." (PMID 39075640, 2024). "In contrast, ARHGAP18 upregulation correlates with favorable prognosis in breast cancer." (PMID 34307347, 2021). "However, if ARHGAP18 was only expressed in either the nucleus or cytoplasm, it was positively correlated with lymphovascular invasion and higher grade, respectively, in breast cancer." (PMID 32992837, 2020). "As Tcf7l2, Antxr1/Tem8, and Arhgap18 have been associated with human breast and other cancers, these data demonstrate that MMTV-induced insertional mutation remains an important means for identifying genes involved in breast cancer." (PMID 22087314, 2011). "For example, in triple-negative breast cancer (TNBC), the most aggressive molecular subtype, miR-200b suppresses metastasis by targeting Rho GTPase-activating protein 18 (ARHGAP18) and promoting RhoA activation, underscoring the critical role of miR-200b in BC progression." (PMID 39763590, 2024). "Here, we used a high throughput approach to identify additional CISs in MMTV-induced mammary tumors and found several novel MMTV target genes including Arhgap18, Tcf7l2, Prkaca and Antxr1/Tem8 (called Antxr1 from here-on)." (PMID 22087314, 2011).
hepatocellular carcinoma (5 papers, 2018 to 2024). A malignant tumor that arises from hepatocytes. "On the other hand, it acts as tumor suppressor miRNA in metastatic cancer and in an advanced clinical stage of hepatocellular carcinoma by targeting ARHGAP18, Rabl3 and snail which are up-regulated and implicated in migration and metastasis of this type of cancer cells." (PMID 36158686, 2022). "LncRNA CDKN2BAS promoted hepatocellular carcinoma metastasis by regulating the miR-153-5p/ARHGAP18 signaling and predicted the poor prognosis in HCC patients." (PMID 33391449, 2021).
leukemia (3 papers, 2021 to 2022). A malignant (clonal) hematologic disorder, involving hematopoietic stem cells and characterized by the presence of primitive or atypical myeloid or lymphoid cells in the bone marrow and the blood. "In leukemia, HOTAIRM1 was considered to be unfavorable and it could activate RHOA/ROCK1 pathway to enhance glucocorticoid resistance by inhibiting ARHGAP18." (PMID 35087800, 2021). "Further study determined that HOTAIRM1 bound to the transcriptional inhibitory region of ARHGAP18 and repressed the expression of ARHGAP18, which led to the increase of RHOA/ROCK1 signaling pathway and promoted GC resistance through antiapoptosis of leukemia cells." (PMID 34262023, 2021).
atherosclerosis (2 papers, 2020 to 2021). A disease characterized by the build-up of fatty material and calcium deposition in the arterial wall resulting in partial or complete occlusion of the arterial lumen. "Recently, the role of ARHGAP18 has been extensively studied in the context of atherosclerosis, a chronic inflammatory disease of the arteries." (PMID 33092266, 2020).
lymphoma (2 papers, 2014 to 2020). A malignant (clonal) proliferation of B- lymphocytes or T- lymphocytes which involves the lymph nodes, bone marrow and/or extranodal sites. "In addition, we also found that the expression of ARHGAP18 (the protein encoded by the SENEX gene) was significantly increased in senescent lymphoma cells." (PMID 33015970, 2020). "In addition, we have identified a panel of novel transcriptional targets including IFI27, IFI44, GBP1, CFLAR and ARHGAP18 for IRF4 in lymphomas." (PMID 25207815, 2014).
Crohn disease (1 paper, 2021). A gastrointestinal disorder characterized by chronic inflammation involving all layers of the intestinal wall, noncaseating granulomas affecting the intestinal wall and regional lymph nodes, and transmural fibrosis. "Our results indicate that the ATG16L1 T300A Crohn's disease-associated SNP causes a decrease in migration capacity in epithelial cells, mediated by an increase in SQSTM1 and ARHGAP18 protein and subsequent reduced RhoA activation." (PMID 33973626, 2021).
latent infection (1 paper, 2014). "Moreover, we profiled the IRF4 transcriptome in the context of EBV latent infection, and confirmed several genes including IFI27, IFI44, GBP1, and ARHGAP18, as well as CFLAR as novel targets for IRF4." (PMID 25207815, 2014).
neurofibromatosis type 1 (1 paper, 2017). A clinically heterogeneous, neurocutaneous genetic disorder characterized by cafe-au-lait spots, iris Lisch nodules, axillary and inguinal freckling, and multiple neurofibromas. "Recurrent chromosomal imbalances affecting the ARHGAP18 locus were observed in six of nine patients with neurofibromatosis type 1." (PMID 28384650, 2017).
cancer (8 papers, 2011 to 2025). A tumor composed of atypical neoplastic, often pleomorphic cells that invade other tissues. "miR-153 has been reported to inhibit the proliferation and invasion of cancer cells through various targets, including Rabl3, ARHGAP18, SNAI1, and Wnt/β-catenin." (PMID 39866238, 2025). "In endothelial cells, ARHGAP18 was shown to act preferentially on RhoC, whereas in cancer cells it shows specificity mainly for RhoA." (PMID 33092266, 2020). "ARHGAP18 was found to regulate cell polarization, cell shape and migration of cancer cells." (PMID 33092266, 2020). "However, the effect of ARHGAP18 expression in cancer cells is still contradictory in individual studies, since inhibition of cancer cell migration, invasion and tumor growth was observed after both overexpression and downregulation of ARHGAP18." (PMID 33092266, 2020). "Again genes involved in other cancer-relevant processes such as cell proliferation, migration, differentiation, apoptosis, or cytoskeletal remodeling were among the driver candidates (all underexpressed with reduced copy number: ARHGAP18, DUSP10, PAK7, PDGFC, RNF217)." (PMID 31682594, 2019). "ARHGAP18 is a member of RhoGAP gene family, which promotes GTP hydrolysis and inactivates RhoGTPase, but the effects of ARHGAP18 in cancer remain controversial." (PMID 30510148, 2018). "We showed that phosphorylation of ARHGAP18 by PKN3 leads to activation of its GAP domain and contributes to regulation of active RhoA levels, implying the possible crosstalk of PKN3 and ARHGAP18 signaling in cancer and other diseases." (PMID 33092266, 2020).
tumor (7 papers, 2011 to 2024). "miR‐200b's modulation of ARHGAP18 is observed to activate RhoA, leading to enhanced formation of adhesion sites and actin stress fibres, ultimately reducing tumour cell migration and metastatic potential." (PMID 39075640, 2024). "The ARHGAP18 gene is involved in endothelial cell regulation and tumor angiogenesis, while the PKD2 protein which contains six transmembrane domains, plays a key role in autophagy, which is an intracellular degradation process under stressful stimuli." (PMID 39001376, 2024). "Two tumors including one tumor with insertion near Arhgap18 (BN) showed higher expression of this gene." (PMID 22087314, 2011). "This suggests that ARHGAP18 may be related to the immune response of monocyte‐derived macrophages in tumours." (PMID 39075640, 2024). "Furthermore, the lncRNA CDKN2BAS/miR-153–5p/ARHGAP18 and RP11-386G11.10/miR-345–3p/HNRNPU networks, upregulated in HCC tissues, correlated with larger tumor size, advanced TNM stage, and poorer prognosis in patients." (PMID 38357004, 2024). "Moreover, both ARHGAP18 and EMP1 might work as tumour suppressors." (PMID 23119007, 2012).
infection (2 papers, 2015 to 2023). The state of being infected such as from the introduction of a foreign agent such as serum, vaccine, antigenic substance or organism. "Infection with an ARHGAP18-encoding adenovirus induced senescence in approximately 20% of the cells at 48 h post infection, as defined by the enlarged cell size, positive staining with SA-β-gal, p21 expression and loss of eNOS expression." (PMID 25407919, 2015).
ARHGAP18 also shares sentences with these, for which no sentence is quoted: bladder cancer (3 papers); diffuse large B-cell lymphoma (2); triple-negative breast carcinoma (2); bipolar disorder (1); cognitive defects (1); Intellectual disability (1); migraine without aura (1); neurological diseases (1); Obesity (1); Sepsis (1); thoracic aortic aneurysm (1).